RNU1-91P (RNA, U1 small nuclear 91, pseudogene)
Gene: Small nuclear RNA gene on chromosome 11 (3,048,359 to 3,048,521, reverse strand). Ensembl gene ENSG00000201616.
Homologues: Orthologues: chimpanzee U1 (98% identical), macaque U1 (88% identical). Paralogues in human: RNU1-1 (82% identical), RNU1-2 (82% identical), RNU1-27P (82% identical), RNU1-28P (82% identical), RNU1-3 (82% identical), RNU1-4 (82% identical), RNVU1-18 (82% identical), RNVU1-29 (82% identical), U1 (82% identical), RNU1-89P (82% identical), RNVU1-28 (82% identical), RNVU1-31 (82% identical), and 133 more.